TLR2 (toll like receptor 2)
Diseases named in the same sentence as TLR2 in open-access papers (continued):
Sharing a sentence is not in itself a finding about the gene and the disease.
Obesity (127 papers, 2009 to 2026). Accumulation of substantial excess body fat. "TLR2 (Arg753Gln) genotypes and alleles as independent risk factors for obesity and MetS were identified by regression analysis calculating the odds ratios (ORs) and 95% confidence interval (CI)." (PMID 39837875, 2025). "Mature-onset obesity has been reported for various murine knockout models, e.g. for IL-1R, IL-6, p62, TLR2 and OTR, and is now also linked with HDAC5 deficiency." (PMID 39304061, 2024). "In C57BL/6 mice with high-fat diet-induced obesity, naringenin suppressed the expression of toll-like receptor 2, which is associated with obesity-induced inflammation that causes insulin resistance and T2D." (PMID 39572023, 2024). "We found that the C allele of the TLR2 gene (rs3804099) was associated with a threefold increase in risk of obesity in elderly patients due to more active TLR-promoted inflammation." (PMID 35207726, 2022). "Studies have revealed that abnormalities in TLR4 and TLR2 are associated with cardiovascular and cerebrovascular diseases, obesity, diabetes, tumors, and metabolic diseases." (PMID 36496853, 2022). "We previously showed that the elevated adipose gene expression of TLR4, TLR2, and MyD88 in people with obesity/T2D was associated with the IRAK1 gene expression." (PMID 36552771, 2022). "In contrast to mice, in humans, the association of the TLR2 gene with obesity is documented, and missense variant rs5743708 G correlates with a higher risk of morbid obesity." (PMID 34834553, 2021). "Innate immune receptors, in particular the Toll-like receptors (TLRs) family, are likely to be involved in obesity-associated inflammatory signaling as the over-expression of TLR2 and TLR4 has been observed in the adipose tissue of obese individuals." (PMID 32708964, 2020). "In agreement, certain disorders such as obesity and type 2 diabetes—characterized by the existence of a chronic low-grade inflammatory state —have been associated with increased TLR2/4 activation." (PMID 31936430, 2020). "TLR2 has been implicated in the pathogenesis of obesity and insulin resistance in dietary mouse models." (PMID 31582899, 2019). "TLR2/4 activation causes a proinflammatory response in autoimmune diseases and contributes to an obesity-induced inflammatory response by increasing TNF-a and IL-6 levels in RA and TNF-a, IL-6, IL-23, and IL-10 levels in SLE." (PMID 31788032, 2019). "In obesity, in addition to an increased intake of saturated fatty acids, TLR4 and TLR2 expression are increased in the AT, further supporting the role of these receptors in obesity-associated inflammatory signaling." (PMID 32063863, 2019). "For example supply of citrus flavonoid is not only beneficial in obesity-related diseases but was furthermore linked to its’ modulating effects on TLR2 expression." (PMID 24432024, 2014). "Previous in vivo studies have implicated TLR2 in the pathogenesis of obesity and metabolic disorders." (PMID 24064574, 2013). "We identified the TLR2 signaling pathway as most deregulated canonical pathway with IRAK3 as downregulated key inhibitor that is associated with obesity-associated metabolic syndrome and loss of protective action of adiponectin against cardiovascular disease." (PMID 22272346, 2012). "Here, we identified IRAK3 as a key inhibitor of TLR2/NFκB-mediated chronic inflammation that is negatively associated with oxidative stress, and obesity-related insulin resistance and metabolic syndrome." (PMID 22272346, 2012). "Serum Wnt5a, leptin, and TNF-α levels increase in women with obesity and the A allele of TLR2 (Arg753Gln) SNP could be protective against obesity-associated metaflammation." (PMID 39837875, 2025). "A previous study found that long-term PM2.5 exposure in mice leads to obesity via TLR4/Ikbke, which increased the risk of obesity and metabolic syndrome, and inflammatory activation regulated by TLR2/4 and lung lipid oxidation lead to abnormal metabolic function and obesity." (PMID 35392463, 2022).
Obesity (continued). "To determine whether the elevated TLR2 expression was the cause of obesity and insulin resistance in the offspring-pLPS mice, we further tested whether TLR2-deficiency reversed the obesity and insulin resistance in the offspring-pLPS mice." (PMID 31507457, 2019). "This phenomenon may explain the relatively mild obesity and insulin resistance phenotype in both offspring-pLPS and TLR2-deficient offspring-pLPS." (PMID 31507457, 2019). "As TLR2-deficiency was previously shown to prevent the pathogenesis of obesity, we initially hypothesized that the TLR2-deficiency would rescue prenatal LPS exposure-induced offspring obesity." (PMID 31507457, 2019). "This suggests that altered intestinal flora, associated with obesity, may activate downstream inflammatory pathways through MyD88 leading to increased systemic TLR2 and 4 levels and a pro-inflammatory environment." (PMID 27992443, 2016). "Obesity and type 2 diabetes are associated with increased expression of TLR2." (PMID 23213270, 2012). "Because obesity and insulin resistance may be promoted by fatty foods in people, the researchers compared the effects of high-fat diets on TLR2-deficient and wild-type mice." (PMID 22162951, 2011). "A deeper understanding of the mechanisms that regulate TLR2 signaling in adipocytes may contribute to unraveling the causes of obesity-induced inflammation and insulin resistance." (PMID 19348674, 2009). "Interestingly, obesity and type 2 diabetes are also associated with increased expression of TLR2, and obesity induces the expression of a subset of adipocytes that over express both TLR2 and TNFα." (PMID 19348674, 2009). "Obesity and type 2 diabetes are associated with increased expression of TLR2, this receptor could play a significant but previously unrecognized role in the establishment of chronic inflammation in adipose tissue in obesity." (PMID 19348674, 2009). "Furthermore, Himes and Smith found that TLR2-deficient mice showed reduced adipocyte hypertrophy, macrophage infiltration, and production of inflammatory cytokines in adipose tissue, as well as protection against diet-induced obesity and insulin resistance." (PMID 39837875, 2025). "Also, the increased circulating lipoproteins in obesity stimulate TLR2, causing adipocytes and macrophages to secrete less adiponectin and to produce pro-inflammatory cytokines, predisposing to leptin resistance in the central nervous system and insulin resistance peripherally." (PMID 39837875, 2025). "Maternal pre-pregnancy or first trimester obesity showed inconsistent effects on offspring birth weight; however, it is associated with alterations in multiple immune parameters and may induce placental inflammation via the macrophage TLR2-NF-κB-p38 signaling pathway." (PMID 42317312, 2026). "In conclusion, WEAF and its key active compounds, glycitein and isorhapontigenin, effectively ameliorate obesity-induced NAFLD via the NF-κB/PPAR-γ signaling pathway by targeting TLR2, supporting their potential as therapeutic target and agents for NAFLD." (PMID 41577727, 2026). "Conversely, another study identifies TLR2 as playing a role in the hypothalamic regulation of metabolism and protection against obesity." (PMID 40558558, 2025). "In line with this, increased TLR2 expression levels have also been reported in the peripheral blood of both obesity and diabetes subjects." (PMID 40558558, 2025). "Excessive activation of TLR2 is associated with chronic LGI, as expressed by the high-sensitivity CRP levels in individuals with metabolically healthy obesity." (PMID 40864791, 2025). "It was proved that TLR2 ablation in mice with obesity decreases adipose tissue metaflammation and improves glucose tolerance, promoting TLR2 as a therapy target to prevent subsequent complications." (PMID 39837875, 2025).
Obesity (continued). "Here we have shown causal mechanistic links between the P. faecium-induced M2 increases via TLR2 and the reduction of the obesity-induced ILC1 increases, allowing resetting of the gut immune homeostasis in obesity." (PMID 40328980, 2025). "Hair follicles in aging and obesity exhibit a decrease in both TLR2 and its endogenous ligand carboxyethylpyrrole (CEP), a metabolite of polyunsaturated fatty acids." (PMID 38483447, 2024). "Preclinical data have shown that the heat-stable Amuc_1100 protein can reproduce the effects of live and pasteurized cells in protection from diet-induced obesity and is an efficient ligand for signal transduction to Toll-like receptor 2 (TLR2)." (PMID 39421255, 2024). "TLR4 activation enhances metabolic inflammation and insulin resistance and TLR2 via its activation by molecules derived from the gut microbiota favours the onset of obesity." (PMID 41853552, 2024). "Another study elucidated that L. plantarum L-14 extract improved obesity in mice via the Toll-like receptor 2 and AMPK signaling pathways." (PMID 38719777, 2024). "High plasma levels of LPSs can induce a series of proinflammatory responses by activating toll-like receptor-2 (TLR2), TLR4, and TLR5, which ultimately trigger obesity-associated IR." (PMID 39080624, 2024). "In the context of obesity, B. uniformis seems to have a proliferative effect, enhancing the small intestine length and leading to the upregulation of Plag2g2a and Tlr2 gene expression." (PMID 38845049, 2024). "In the context of obesity, TLR2 and TLR4 act as significant mediators that connect excessive food intake and the occurrence of inflammation." (PMID 38276294, 2023). "Another driver of obesity-related inflammation is the activation of toll-like receptors (TLRs), especially TLR-2 and TLR-4." (PMID 37036026, 2023). "Individuals with obesity have higher levels of TLR2 and TLR4 expression in their adipose tissue, indicating that these receptors are implicated in the inflammation-related signaling associated with obesity." (PMID 36421371, 2022). "The body weight curve of TLR2−/−-TLR4−/− mice resembled that of TLR4−/− mice, indicating that the obesity developed by TLR2−/− mice depends on the expression of TLR4." (PMID 36555322, 2022). "It was found that the oral administration of Lactobacillus plantarum can lead to the inhibition of TLR2 in a murine high-fat-diet (HFD) model of obesity." (PMID 35937847, 2022). "A very remarkable result of our study is the reversion of the mature-onset obesity phenotype of TLR2−/− mice by the generation of TLR2−/−TLR4−/− double knockout mice." (PMID 36555322, 2022). "We have observed that obesity induced a remarkable increase in TLR2 gene expression in both PBMC and PMN while TLR4 mRNA levels remained unchanged." (PMID 35896710, 2022). "Obesity is characterized by low-grade chronic inflammation, possibly triggered by TLR2 and TLR4 activation." (PMID 35721808, 2022). "At the same time, we show that TLR2 knock-out mice spontaneously developed mature-onset obesity and insulin resistance." (PMID 36555322, 2022). "The protein Amuc_1100 isolated from Akkermania muciniphila can interact with Toll-like receptor 2 to repair the intestinal barrier and improve obesity and metabolic disorder." (PMID 36710961, 2022). "EPS from L‐14 extract inhibits adipogenesis via TLR2 and AMPK signalling pathways, and oral intake of L‐14 extract improves obesity and obesity‐associated diseases in vivo." (PMID 33830560, 2021). "In mice, repeated administration of A. muciniphila ameliorates the impact of high-fat diets in inducing obesity and strengthens the function of the GI epithelial barrier though the activation of Toll-like receptor 2 (TLR2)." (PMID 34006653, 2021). "TLR2 and TLR4 contribute to metabolic syndrome associated with HFD-induced obesity, insulin resistance and tissue inflammation." (PMID 32937828, 2020). "On the contrary, TLR2 surface expression in monocytes was unaffected by group of subjects and obesity." (PMID 31936430, 2020).
Obesity (continued). "TLR (Toll-like receptor 2) signaling plays an essential role in obesity as well as metabolic syndrome." (PMID 32598403, 2020). "In our series of young adults, obesity increased fasting TLR2 surface expression but decreased that of TLR4." (PMID 31936430, 2020). "Toll-like receptor 2 (TLR2), which recognizes several lipopeptides and transduces inflammatory signaling, promotes the pathogenesis of diet-induced dyslipidemia and obesity." (PMID 31507457, 2019). "It is elucidated that TLR2 dysregulation during obesity translates a metabolic challenge into an inflammatory response and contributes to obesity-associated metabolic diseases." (PMID 31272370, 2019). "Although TLR2 is elevated in obese patients compared with healthy controls, it is unaltered in patients with limited liver disease compared with obesity-related NASH in two clinical studies." (PMID 31582899, 2019). "Stimulation with TLR2 and 4 ligands, resulted in greater production of pro-inflammatory mediators, potentially due to obesity-induced changes in TLR activation in myeloid cells." (PMID 30131724, 2018). "The significance of TLR2/4 signaling in the pathology of obesity-induced metabolic dysfunctions has been demonstrated in vitro and in knockout mouse models fed a HFD." (PMID 29186929, 2017). "In this sense, research in animal models of obesity-related NAFLD has recently addressed the role of TLR2." (PMID 27834919, 2016). "Despite the role that TLR2 plays in obesity-related NAFLD, the role of TLR6 in this disease remains unveiled." (PMID 27834919, 2016). "Our results add NOD2 as an important PRR to the growing list of immune components that protect against dysbiosis and metabolic disease during obesity, which includes TLR2, TLR5, and inflammasome components." (PMID 25666722, 2015). "The emerging role of TLR2/4 as immuno-metabolic receptors points to key involvement of TLR/IL-1R/MyD88 pathway in obesity/type-2 diabetes (T2D)." (PMID 26312071, 2015). "The immunometabolic role of TLR2 and TLR4 makes these receptors and their associated pathways critical for identifying targets to treat metabolic conditions such as obesity-induced inflammation and type-2 diabetes (T2D)." (PMID 26312071, 2015). "Obesity leads to the enhanced expression of TLR2 and TLR4 on the peripheral blood mononuclear cells which has significant implications with regard to inflammation." (PMID 26312071, 2015). "With the choline-deficient amino acid-defined (CDAA) diet model mouse, which develops steatosis with relatively mild hepatitis with obesity, TLR2 knockout resulted in improvement of NASH." (PMID 24786095, 2014). "Intriguingly, another group reported that TLR2 KO mice exhibit mature-onset obesity by modulating food intake." (PMID 24064574, 2013). "When raised in germ-free environments, mice that lack TLR2 are protected against obesity-induced insulin resistance." (PMID 22162951, 2011). "Therefore, because obesity is a state of chronic inflammation that is associated with increased expression of TLR2 and TLR4, we also tested the hypothesis that activation of TLR2 and TLR4 in adipocytes represents a mechanistic link between inflammation and downregulation of adiponectin receptors." (PMID 19348674, 2009). "Interestingly, obesity persisted in chimeric mice possessing TLR2-positive immune cells, suggesting that the observed effects are mediated through non-immune mechanisms." (PMID 40558558, 2025). "Furthermore, FFAs act as endogenous ligands for the toll-like receptor 2 and 4 (TLR2 and TLR4) complex, causing macrophage cytokine release and regulating AT inflammation, which contributes to obesity-related metabolic syndrome." (PMID 38732619, 2024). "Obesity induced by a high‐fat diet increases PA levels, which can upregulate the expression of intracellular TLR2 and TLR4, generate reactive oxygen species (ROS), increase NF‐κB activity, induce the expression and activity of Toll‐like receptors (TLR), and release inflammatory factors." (PMID 39207121, 2024).
Obesity (continued). "Additionally, particulate matter exposure increased oxidative stress and induced Toll-like receptor 2/4-dependent inflammatory activation in the lung and further spilled over systematically, finally leading to metabolic dysfunction and obesity." (PMID 37876545, 2023). "Specifically, TLR4/TLR2 have emerged as metabolic sensors of lipopolysaccharide (LPS) and saturated free fatty acids (sFFAs), both of which are abundantly found in individuals with obesity and T2D." (PMID 36552771, 2022). "TLRs, especially, the TLR4 and TLR2 have emerged as key players in metabolic inflammation by nutrient sensing of LPS as well as sFFAs, both of which are abundantly found in individuals with obesity/T2D." (PMID 36552771, 2022). "Therefore, a better understanding of the role TLR2/4 expression plays, specifically in intestinal PP, in obesity requires further investigations." (PMID 34083551, 2021). "Moreover, the use of knock-out mice or loss of function mutations in either TLR2, TLR4 or MyD88 also confirmed their role in obesity-associated inflammation." (PMID 34083551, 2021). "To test the hypothesis that TLRs contribute to the development of obesity in offspring with prenatal LPS exposure (offspring-pLPS), we analyzed the mRNA expression levels of two well-studied TLRs, TLR2, and TLR4." (PMID 31507457, 2019). "One puzzling dilemma is that TLR2-deficiency significantly promotes hyperlipidemia in offspring-pLPS without enhancing the severity of obesity and insulin resistance in offspring-pLPS." (PMID 31507457, 2019). "Furthermore, animal models of obesity have established that fatty acid mediated alterations in TLR2 and TLR4 signaling play a central role in the establishment of insulin and leptin resistance." (PMID 30131724, 2018). "Increased TLR2 expression on enteric and hypothalamic neurons was recently reported in the context of obesity and peripheral changes, further confirming the potential of this innate immune pathway in neuronal cells to respond to regionally relevant disease signals." (PMID 27888296, 2017). "Another important issue that may activate proinflammatory potential in obesity is an increase of expression of Toll-like receptors (TLR2, TLR4) on the membranes of various cell types, such as immune and resident non-immune cells, including adipocytes in VAT." (PMID 28103807, 2017). "This could suggest that in Chinese middle-aged men, TLR4-mediated inflammatory signaling may be more related to obesity when compared to TLR2." (PMID 27481183, 2016). "Given that biglycan is released from the ECM under conditions of tissue stress and that unsequestered biglycan is an endogenous ligand for TLR2/4, the relevance of the current findings to the pathogenesis of obesity-related disorders such as insulin resistance warrant further studies." (PMID 27465988, 2016). "Together, these data reveal a certain importance regarding TLR2 role in obesity." (PMID 26635627, 2015). "Also, other studies demonstrated that TLR2 reduced levels protects against obesity and inflammation." (PMID 26635627, 2015). "It was described that TLR2, TLR4, or TLR5 deficiency have a major role on obesity development." (PMID 26635627, 2015). "So, the role of TLR2 in obesity-induced metabolic disorders merits more study in different organs." (PMID 24064574, 2013). "Indeed, a recent report indicates that obesity induces a subset of adipocytes to express both TLR2 and TNFα and exposure of adipocytes to zymosan triggers expression of TNFα." (PMID 19348674, 2009). "Elevated fatty acid concentrations in obesity may amplify the inflammatory cascade that is induced by yet unidentified endogenous ligands for TLR2." (PMID 19348674, 2009). "Since TLR2 expression is induced in obesity and type 2 diabetes, TLR2 may play a prominent role in the initiation of obesity induced inflammation." (PMID 19348674, 2009). "This raises the possibility that activation of TLR2 in obesity may contribute to a state of adiponectin resistance in obesity." (PMID 19348674, 2009).